BRCA2 (BRCA2 DNA repair associated)
Diseases named in the same sentence as BRCA2 in open-access papers (continued):
Sharing a sentence is not in itself a finding about the gene and the disease.
ovarian carcinoma (continued). "We compared the frequency and spectrum of BRCA1 and BRCA2 mutations contributing to breast and ovarian cancer families in Malopolska with those that have been previously reported in Polish families." (PMID 26843898, 2016). "Five BRCA1 and 3 BRCA2 recurrent mutations account for more than half of the patients with proven hereditary breast/ovarian cancer originating from FVG and neighboring geographic areas." (PMID 26852130, 2016). "In this work we demonstrated that pre-cancer SOX2 overexpression in the FTE is nearly ubiquitous in HGSOCs and is also a common feature in women with BRCA1 and BRCA2 mutations prior to ovarian cancer initiation." (PMID 27492892, 2016). "Approximately 8–15% epithelial ovarian cancer patients are BRCA1 or BRCA2 germline mutation carriers." (PMID 27914478, 2016). "Three (23%) of the 13 PDAC patients with a personal history of breast or ovarian cancer had deleterious mutations, two BRCA2 mutations and one ATM mutation, the latter of which was described in the previous section (NCCH-16)." (PMID 27732944, 2016). "The main indications for RRSO are risk-reducing surgery in women at risk of developing ovarian or fallopian tube cancer such as BRCA1 or BRCA2 germline mutations or hereditary (breast) and ovarian cancer (HBOC)." (PMID 26768420, 2016). "Germline mutations in BRCA1 and BRCA2, involved in HR and FA repair, increase the risk of developing breast and ovarian cancer 40-80% and 11-40%, respectively, in addition to other cancer types." (PMID 27004405, 2016). "The ovarian cancer penetrance is lower for BRCA2, with a lifetime risk of 12–25% and an average age of diagnosis of 60 years." (PMID 27463617, 2016). "Evidence of serous tubal intraepithelial carcinoma in risk-reducing salpingo-oophorectomy of asymptomatic women with known BRCA1 or BRCA2 mutations or strong family history of breast or ovarian cancer." (PMID 27200296, 2016). "Genetic inactivation of the major hereditary breast/ovarian cancer predisposition HR genes BRCA1 or BRCA2, or of other HR genes such as the Rad51 paralogs Rad51C, XRCC2 or XRCC3 biases HR in favor of LTGC." (PMID 27832076, 2016). "A phase II clinical trial demonstrated that monotherapy with the PARP inhibitor olaparib (AZD-2281; AstraZeneca) achieved encouraging response rates of 41% and 33% in patients with BRCA1- or BRCA2-mutated advanced breast and ovarian cancers, respectively." (PMID 26967246, 2016). "A total of 8,211 BRCA2 mutation carriers were included in the analysis, of whom 631 were censored at ovarian cancer diagnosis." (PMID 27463617, 2016). "Findings from an international observational study of 19,581 BRCA1 and 11,900 BRCA2 carriers from 55 centers in 33 countries on 6 continents provide strong evidence that breast and ovarian cancer risks vary by type and location of BRCA1/2 mutation." (PMID 27242959, 2016). "Women who are carriers of BRCA1 mutations present with a 39–46 % lifetime risk of developing ovarian cancer, and for carriers of BRCA2 mutations the lifetime risk is 12–20 %." (PMID 27468354, 2016). "Although germline mutations in the tumor suppressor BRCA1 and BRCA2 genes are associated with a high risk of breast and ovarian cancer, however, they have also been shown to correlate with other cancers, including gastric cancer." (PMID 26779294, 2016). "Monoallelic germline mutations in the tumour suppressor genes BRCA1 and BRCA2 predispose women to breast and ovarian cancer." (PMID 27037238, 2016). "In summary, in this study we demonstrated that SOX2 overexpression occurs in a fraction of women with BRCA1 and BRCA2 mutations prior to ovarian cancer initiation and in the majority of patients with HGSOCs irrespective of tumor stage." (PMID 27492892, 2016). "Gastric cancer (GC) is part of the spectrum of diseases linked to BRCA1 and BRCA2 mutations that increase the risk of breast and ovarian cancer." (PMID 26779294, 2016).
ovarian carcinoma (continued). "BRCA1 and BRCA2 screening for mutations was carried out on 1114 breast and/or ovarian cancer patients complying with the eligibility criteria for BRCA testing." (PMID 26852130, 2016). "Taken together, these results indicate that in both BRCA1 and BRCA2 mutation carriers there is only one peak of association with ovarian cancer risk at 9p22." (PMID 27463617, 2016). "Germline mutations in the BRCA1 and BRCA2 genes are the most important causes of hereditary breast and ovarian cancer." (PMID 26967246, 2016). "Based on our results, the frequency of BRCA1 and BRCA2 mutations among Moroccan women with hereditary breast and/or ovarian cancer is 25.64 %." (PMID 27129401, 2016). "Olaparib, a PARP1 inhibitor, is now approved for patients with advanced ovarian cancer harboring BRCA1 or BRCA2 deleterious mutations, as loss of BRCA sensitizes these tumors to further inhibition of DNA repair and results in a synthetic lethality." (PMID 27004405, 2016). "In Colombia, a study conducted by Torres and collaborators found a frequency of 24.5% of deleterious BRCA1/BRCA2 mutations in a cohort of 53 breast/ovarian cancer families evaluated." (PMID 27741520, 2016). "Several studies have reported somatic BRCA1 and BRCA2 mutations in a considerable proportion of breast and ovarian cancers." (PMID 27533253, 2016). "A total of 23 deleterious mutations of BRCA1 and BRCA2 were identified in 31 familial breast/ovarian cancer patients, and the frequency was 23.3 % (31/133)." (PMID 26852015, 2016). "Germline mutations in the BRCA1 and BRCA2 genes greatly increase a woman’s risk of developing breast and/or ovarian cancer." (PMID 26852015, 2016). "The role of germline mutations in BRCA1 and BRCA2 genes in the risk of the development of ovarian cancer is clinically well established." (PMID 26753012, 2016). "BRCA1 and BRCA2 mutations accounted for a considerable proportion of hereditary breast/ovarian cancer patients from eastern China and the spectrum of the mutations of these two genes exhibited some unique features." (PMID 26852015, 2016). "On December 2014 the European Medicines Agency (EMA) and the U.S.A. Food and Drug Administration (FDA) approved the PARPi olaparib for treatment of BRCA1/BRCA2 mutated ovarian cancer." (PMID 26745875, 2016). "Germline mutations in BRCA1 and BRCA2 are the most penetrating genetic predispositions for breast and ovarian cancer, and their presence is largely ethnic-specific." (PMID 26848529, 2016). "There are only a few studies that have analyzed the frequency of BRCA1/BRCA2 mutations in fallopian tube and peritoneal cancer independently of ovarian cancer." (PMID 27532258, 2016). "The largest and most recent meta-analysis demonstrated that BRCA1 and BRCA2 mutations have positive prognostic effects on ovarian cancer overall and progression-free survival." (PMID 27004793, 2016). "BRCA1 and BRCA2 are among the most frequently mutated genes in high-grade ovarian serous carcinoma, which is responsible for the vast majority of ovarian cancer deaths." (PMID 26745875, 2016). "Detailed analyses showed that the only prognostic factor for OS in ovarian cancer was mutated BRCA2 (HR 0.33; 95 % CI: 0.16–0.69, p = 0.003)." (PMID 26753012, 2016). "Germline mutations in breast and ovarian cancer susceptibility genes, BRCA1 and BRCA2, significantly increase lifetime risk of developing ovarian cancer compared to the general population." (PMID 27588493, 2016). "The BRCA1 and BRCA2 tumour suppressor genes are the most important predisposition genes for ovarian cancer and account for about 90 % of ovarian cancers in the hereditary breast and ovarian cancer syndrome." (PMID 26560874, 2016). "Approximately 15% of ovarian cancer patients have a germline BRCA1 or BRCA2 mutation which has substantial implications for their personal management and that of their relatives." (PMID 27406733, 2016).
ovarian carcinoma (continued). "A recent study demonstrated that both germline (inherited) and somatic (acquired) loss-of-function mutations in BRCA1 and BRCA2 genes predict higher rates of platinum sensitivity and better overall survival (OS) in primary ovarian carcinoma." (PMID 28003870, 2016). "Germline losses in BRCA1/BRCA2 are highly penetrant, conferring 60–80 % risk of breast and 30–40 % risk of ovarian cancers." (PMID 26427375, 2015). "The high incidence of germline BRCA1 and BRCA2 mutations in ovarian cancer, has suggested that genetic assessment of women with ovarian cancer especially those with nonmucinous high-grade serous histology, will improve mutation carrier detection rates." (PMID 25884701, 2015). "A previously published Markov model of PAC was updated and extended to incorporate key aspects of BRCA2 mutation carrier status, including competing risks of breast- and ovarian-cancer specific mortality." (PMID 26844277, 2015). "Of these, BRCA1 and BRCA2 appear to account forapproximately two-thirds of germline mutations in ovarian cancer, with smallercontributions from the remaining genes." (PMID 26669451, 2015). "Germline mutations in these genes represent significant risk factors for developing HGSOC: for a woman with a BRCA1 mutation, the risk of developing epithelial ovarian cancer is 39–46%, and with a BRCA2 mutation, 12–20%." (PMID 26579492, 2015). "Inheritance of a deleterious mutation in either of the BRCA1 or BRCA2 genes greatly increases a woman's lifetime risk of developing breast and ovarian cancers." (PMID 26246475, 2015). "While the BRCA2 mutation is best known for its associated elevated breast and ovarian cancer risk, it also conveys an increased risk of pancreatic adenocarcinoma (PAC) as the most common genetic alteration found in familial pancreatic cancer." (PMID 26844277, 2015). "There were 31 women, 21 BRCA1 and 10 BRCA2 mutation carriers, with a previous diagnosis of ovarian cancer, and four of them (2 BRCA1 and 2 BRCA2 mutation carriers) subsequently developed a breast tumor." (PMID 26163143, 2015). "Ovarian carcinoma occurs at younger age in BRCA1 mutation carriers than in BRCA2 mutation carriers or the general population (both mean and median 51 versus 56 versus 60 years respectively)." (PMID 26286255, 2015). "Tumor suppressor genes BRCA1 and BRCA2 are the two main breast and ovarian cancer susceptibility genes, and their genetic testing has been used to evaluate the risk of hereditary breast and ovarian cancer (HBOC)." (PMID 25802882, 2015). "PARP functions in the base excision repair (BER) pathway to repair SSBs, and inhibitors have been found to stabilize or regress ovarian cancer with BRCA1/BRCA2 mutations." (PMID 26579492, 2015). "Bilateral salpingo-oophorectomy should be offered to women with a BRCA1 or BRCA2 mutation, between 35 and 40 years and after completion of childbearing, or individualise based on the earliest age of ovarian cancer diagnosed in the family." (PMID 26669313, 2015). "The association of germline mutations in the breast cancer susceptibility gene 1 (BRCA1) and the breast cancer susceptibility gene 2 (BRCA2) with the development of breast and ovarian cancers have been widely researched and recognised." (PMID 26236408, 2015). "The Association of Gynecologic Oncology recommends that testing for a germline mutation in BRCA1 or BRCA2 should be offered to all patients with epithelial ovarian cancer." (PMID 26109557, 2015). "We thus, performed this meta-analysis to derive a more precise and up-to-date estimation of the association between BRCA2 N372 and ovarian cancer risk." (PMID 26496279, 2015). "Approximately 15 % of the patients with epithelial ovarian cancer have a germline mutation in the BRCA1 or BRCA2 genes." (PMID 26109557, 2015). "BRCA1 and BRCA2 mutations in ovarian cancers, are associated with defects in homologous recombination and genomic instability." (PMID 25537514, 2015).
ovarian carcinoma (continued). "All the data in these included studies were related to the association between BRCA2 N372H polymorphism and human ovarian cancer risk." (PMID 26496279, 2015). "Several FA genes are also breast and ovarian cancer susceptibility genes (FANCD1/BRCA2, FANCJ/BRIP1, FANCN/PALB2, FANCO/RAD51C, and FANCS/BRCA1)." (PMID 26430909, 2015). "Recent findings, however, have shown that up to 15 % of patients with epithelial ovarian cancer have germline mutations in BRCA1 or BRCA2." (PMID 26109557, 2015). "Identifying carriers of BRCA1 and BRCA2 mutations allows for the targeted prevention of ovarian cancer in family members of ovarian cancer patients." (PMID 25884701, 2015). "Bilateral salpingo-oophorectomy should be offered to women with a BRCA1 or BRCA2 mutation, between 35 and 40 years and after completion of childbearing, or individualised based on the earliest age of ovarian cancer diagnosed in the family (II,A)." (PMID 26669313, 2015). "In the overall analysis, the results showed a significant association between BRCA2 codon 372 polymorphism and increased risk of ovarian cancer (HH versus NN: odds ratio (OR) = 1.22, 95% confidence interval (CI) 1.01–1.48, P = 0.037)." (PMID 26496279, 2015). "The benefits of BRCA1 and BRCA2 testing for women with breast and/or ovarian cancers, women with a family history and/or elevated risk, or even all women, are evident." (PMID 26543556, 2015). "Based on a series of basic, preclinical and clinical studies, the Poly (ADP-ribose) Polymerase 1 (PARP1) inhibitor, olaparib, has recently been approved for use in ovarian cancer patients with BRCA1 or BRCA2 mutations." (PMID 25883215, 2015). "It is also important to note that none of the studies summarized above reports any data on BRCA1 or BRCA2 mutation carriers and the results should only be generalized to women at population-level risk for ovarian cancer." (PMID 27231565, 2015). "The most important predisposition genes BRCA1 and BRCA2, conferring high life-time risks of breast and ovarian cancer, are involved in the homologous recombination repair (HRR) of DNA double-strand breaks (DSB)." (PMID 25918678, 2015). "The likelihood of harbouring a germline BRCA1/BRCA2 mutation depends on the histological subtype and/or tumour grade of epithelial ovarian cancers." (PMID 25884701, 2015). "This, combined with anexpanding range of clinical implications for ovarian cancer patients found to carrya BRCA1 or BRCA2 mutation, has presented a central role forgenetic testing." (PMID 26669451, 2015). "The majority of mutations found to date in the BRCA1/BRCA2 genes in breast and/or ovarian cancer families are point mutations or small insertions and deletions scattered over the coding sequence and splice junctions." (PMID 25632310, 2015). "The present meta-analysis also indicated that there exists a much stronger association between BRCA2 N372H polymorphism with ovarian cancers of the serous subtype compared with other ovarian cancer subtypes." (PMID 26496279, 2015). "In the overall analysis, we found a significant strong association between BRCA2 N372H polymorphism and increased risk of ovarian cancer in the homozygote model (HH versus NN) with OR 1.22 (95% CI, 1.01–1.48, P = 0.037)." (PMID 26496279, 2015). "Inhibition of PARPs is a promising strategy for targeting cancers with defective DNA-damage repair, including BRCA1 and BRCA2 mutation-associated breast and ovarian cancers." (PMID 26268938, 2015). "When mutations in BRCA1, BRCA2, or other cancer-susceptibility genes have been identified, patients with ovarian carcinoma can be treated with new, innovative therapies." (PMID 26109557, 2015). "Mutations in the BRCA1 and BRCA2 genes lead to an increased risk of developing breast or ovarian cancer as part of hereditary breast-ovarian cancer syndrome." (PMID 25859162, 2015). "Germline mutations of BRCA2 are associated with increased risk for developing breast and ovarian cancer." (PMID 25569148, 2015).
ovarian carcinoma (continued). "For example, germline mutations in BRCA1 or BRCA2 are associated with ovarian cancer at a rate of only 20–40%, suggesting the presence of other unidentified mutations in other genes as an etiology." (PMID 26301412, 2015). "To analyze the prevalence of HBOC with BRCA1 and BRCA2 germline mutations, we recruited 135 breast and/or ovarian cancer survivors and extracted DNA from their peripheral blood lymphocytes." (PMID 25802882, 2015). "Overall, BRCA1 and BRCA2 mutation carrier frequencies of 13-15% have been reported for ovarian cancer patients from the general population." (PMID 25884701, 2015). "The frequency of BRCA1 and BRCA2 mutations in ovarian cancer patients varies depending on histological subtype and population investigated." (PMID 25884701, 2015). "BRCA1 and BRCA2 germline mutations are associated with high penetrance for both breast and ovarian cancer." (PMID 25366421, 2015). "Germline mutations in BRCA1 and BRCA2 genes are the most frequent cause of strong genetic predisposition to breast and ovarian cancer." (PMID 26163143, 2015). "It is well established that germline mutations in BRCA1 and BRCA2 confer susceptibility to breast and ovarian cancers." (PMID 26622941, 2015). "Hereditary breast and ovarian cancer is an inherited genetic condition associated with a mutation in the BRCA1 or BRCA2 gene." (PMID 26557407, 2015). "Mutations of the tumor suppressor genes BRCA1 and BRCA2 are known to be associated with different patterns of hereditary breast and ovarian cancer." (PMID 25885768, 2015). "We found five E3002K mutation-positive carriers in the cohort of 439 women with ovarian cancer, which is similar in frequency to the number of carriers of each of the other three BRCA2 (8765delAG, G6085T, 3398del5) mutations in the same cohort." (PMID 25884701, 2015). "In a recent meta-analysis of case–control studies in BRCA1 and BRCA2 mutation carriers, a significant 50 % risk reduction of ovarian cancer was associated with the past use of combined oral contraceptives." (PMID 26669313, 2015). "Germ-line mutations in BRCA1 and BRCA2 tumor suppressor genes cause a hereditary predisposition to breast and ovarian cancer." (PMID 24906410, 2014). "Germline mutations in BRCA1 or BRCA2 are present in approximately 18% of hereditary ovarian cancers." (PMID 25051360, 2014). "In summary, we have identified at least two SNPs, rs1466785 and rs2304277, in the DNA glycolylases NEIL2 and OGG1, potentially associated with increased breast and ovarian cancer risks in BRCA2 and BRCA1 mutation carriers, respectively." (PMID 24698998, 2014). "Women harboring a germ-line mutation in the BRCA1 or BRCA2 genes have a high lifetime risk to develop breast and/or ovarian cancer." (PMID 24698998, 2014). "Mutations of BRCA1 and BRCA2 tumor suppressor genes are responsible for most hereditary ovarian cancers." (PMID 24821107, 2014). "Majority of mutations found to date in the BRCA1and BRCA2 genes in breast and/or ovarian cancer families are point mutations or small insertions and deletions scattered over the whole coding sequence and the splice junctions." (PMID 24906410, 2014). "Recently, next generation sequencing methods for the mutation analysis of the BRCA1 and BRCA2 genes in patients with breast and ovarian cancer have been described using both high capacity and bench top platforms." (PMID 25136594, 2014). "We next decided to implement our parallel pyrosequencing protocol and sequence analysis approach to screen for mutations in the BRCA1 and BRCA2 genes in a series of 101 patients with breast and ovarian cancer." (PMID 25136594, 2014). "Based on the diagnostic criteria used in the United States to select patients to be tested, clearly pathogenic mutations in either BRCA1 or BRCA2 are found in 10% to 15% of hereditary breast and ovarian cancer families." (PMID 25136623, 2014).